ATG7 (autophagy related 7)
Diseases named in the same sentence as ATG7 in open-access papers (continued):
Sharing a sentence is not in itself a finding about the gene and the disease.
tumor (continued). "Specifically, depletion of autophagy related 5 (ATG5) or autophagy related 7 (ATG7) (loss of autophagy), or acyl-CoA synthetase short chain family member 2 (ACSS2) (acetate recapture loss) is well tolerated by most cells in culture, but can dramatically decrease tumor growth in vivo." (PMID 30104199, 2018). "Interestingly, mice with an Atg7 conditional knockout in the liver developed multiple tumors in this tissue and this phenotype was reversed by p62 knockout, indicating that p62 accumulation due to autophagy suppression contributes to tumor formation." (PMID 30622432, 2018). "In an in vitro model, ATG7 knockdown significantly inhibited cellular proliferation and colony formation as well, suggesting that ATG7-mediated autophagy may be involved in cell proliferation and tumor growth of pediatric NB." (PMID 29311760, 2018). "The effect of ATG7 silencing and autophagy inhibition on sensitivity to PI3K inhibitors results in accumulation of p62/SQSTM1, which is associated with increased anti-oxidant response and tumor cell survival and, in fact, increased p62/SQSTM1 expression is observed in primary SCCHN tumors." (PMID 24599075, 2014). "Similarly, growth inhibition induced by gefitinib or erlotinib in A549 cells was enhanced after autophagy was inhibited by the knockdown of ATG5 or ATG7, two essential components for the formation of autophagosome, confirming that autophagy protected tumor cells from EGFR-TKIs induced cell death." (PMID 21655094, 2011). "BCc1 exhibits a dual regulatory effect—upregulating tumor-suppressive Beclin-1 while downregulating pro-survival ATG-4B, ATG-7, and mTOR—in a manner dependent on dose and administration route." (PMID 41550506, 2026). "Our study sought to delineate the molecular underpinnings of BCc1's anti-tumor effects in a BALB/c murine model of BC, focusing on key autophagy regulators (Beclin-1, ATG-4B, ATG-7) and the mTOR signaling axis." (PMID 41550506, 2026). "Almost all solid tumors highly express ATG5, ATG7, ATG6L1, and secretion-related genes such as RABs, revealing the interaction between tumor progression and intracellular cargos transport." (PMID 39893499, 2025). "Mice with liver-specific Atg7 knockout develop liver tumors, while knockout of SQSTM1/p62 reduces tumor size." (PMID 40229278, 2025). "ATG7 has also been shown to inhibit the Warburg effect by suppressing PKM2 phosphorylation, which reduced the epithelial-mesenchymal transition of tumor cells." (PMID 40707430, 2025). "In vivo, co-administration of the sh-RPS6KA2 plasmid and cisplatin significantly increased the expression of ATG5, ATG7, and BECN1, as well as promoted subcutaneous tumor growth compared to cisplatin monotherapy." (PMID 41502518, 2025). "In contrast, administration of the RPS6KA2 overexpression plasmid together with cisplatin reduced the expression of ATG5, ATG7, and BECN1 and inhibited tumor expansion." (PMID 41502518, 2025). "BECN1, ELAVL1, and ATG16L1 were highly expressed in tumor tissues, while NCOA4, FTH1, FTL, SNCA, TNF, ATG7, and ZFP36 showed low expression levels." (PMID 39593730, 2024). "Our results are supported by a recent study showing that conditional whole‐body deletion of the autophagy gene Atg7 induces a type I and II IFN response in urothelial tumors resulting in the release of inflammatory cytokines and anti‐tumor immunity induction." (PMID 38506049, 2024). "We established stable MEF clones overexpressing the Atg5 transgene in the background of Atg7 gene knockout (Atg7−/‐MEF), which showed increased cell proliferation, migration, and colony formation in vitro, and transient induction of tumor formation in vivo." (PMID 38826147, 2024). "Others have demonstrated that silencing of autophagy-related 7 (ATG7) expression, a protein essential for autophagy, in KRASG12D/LKB1null-driven tumors at the time of tumor initiation substantially diminishes lung tumor burden." (PMID 39213022, 2024).
tumor (continued). "Other studies have found that in human glioblastoma xenografts, knockdown of ATG7 combined with treatment with the VEGF-neutralizing antibody bevacizumab disrupted tumor growth and helped prevent tumor resistance to anti-angiogenic therapy." (PMID 38786047, 2024). "The mRNA levels of HO‐1, ATG7, and LC3B were increased in the tumor tissues of 1‐D‐6‐G‐treated xenograft mice than in Con‐T mice." (PMID 39402821, 2024). "Autophagic genes, including Atg5, Atg7, and ULK, are overexpressed in detached cells from glioblastoma, thus preventing anoikis and promoting tumour growth." (PMID 37174088, 2023). "In HCT116 and HT29 cells, the pathogen promoted the activation of tumor autophagy, increasing the expression of the phosphorylated AMPK (pAMPK), pULK1, ULK1 and ATG7." (PMID 36835075, 2023). "In tumor tissues of HCV-HCC, compared with para-tumor tissues, the expression of LC3B, Beclin1, and ATG7 was upregulated." (PMID 38003445, 2023). "We have proved that FBXW7 regulate tumor cell autophagy through the regulation of the protein levels of BECN1, Atg7, and LC3." (PMID 37249289, 2023). "The miR‐4736 antagomir‐treated group showed stagnancy in tumor growth as manifested by smaller tumor volume, decreased levels of fibronectin, collagen 1, α‐SMA, and Ki67, and increased levels of ATG7." (PMID 36727832, 2023). "Some other ATG genes and proteins have also been suggested to be tumor suppressors since deletion of ATG5 and ATG7 induces the development of benign liver tumors in mice." (PMID 36814341, 2023). "We further show that inhibiting autophagy by genetical ablation of FIP200, Atg5 or Atg7, significantly inhibited LAS tumor cell proliferation in vitro and tumorigenicity in vivo." (PMID 36813768, 2023). "WWP1 exerts the autophagy inhibitor and the tumor promotor roles in AML cancer cells where it negatively regulates the phagophore nucleation and elongation likely via targeting ATG7 and LC3." (PMID 36918822, 2023). "Since P62 is a well-known receptor for autophagy, we also examined the expression of autophagy markers including ATG7, Beclin-1 and LC3B in xenograft tumor sections by IHC." (PMID 35216629, 2022). "Remarkably, Palb2f/f;Atg7f/f;Wap-Cre (Palb2;Atg7-CKO) mice exhibited greatly reduced overall survival (T50 = 280 days), even though their tumor development was also greatly reduced." (PMID 35404932, 2022). "In patients, for whom mass spectrometry protein data were publicly available from the Clinical Proteomic Tumor Analysis Consortium (CPTAC), BECN1 and ATG7 copy numbers also correlated with the respective protein level." (PMID 35681458, 2022). "We conclude that single copies of the ATG7, BECN1, LC3, and ATG10 gene are largely sufficient to sustain autophagy and maintain tumor cell proliferation under treatment with 2DG and DCA." (PMID 35681458, 2022). "ATG7, a major component of the CK1α/PTEN/FOXO3a/ATG7 axis, has been shown to be involved in the tumor-suppressive process in early LUAD." (PMID 36177001, 2022). "Specific Atg7 and Atg5 ablation of BRAFV600E-driven melanoma inhibits tumour formation and induces melanocyte senescence in GEMMs." (PMID 33802014, 2021). "The protein expression of mTOR and p62 were markedly downregulated, and the protein expression of ATG-7, Beclin-1, and LC3-II/LC3-I were markedly upregulated in the tumor tissues in the QYSL and RAPA groups compared with the model group." (PMID 34093717, 2021). "Meanwhile, the Atg7/YAP double KO mice attenuated hepatomegaly and hepatocarcinogenesis with significantly lower tumor size and number than the Atg7-KO mice." (PMID 33082313, 2020). "We further evaluated the protein expressions of autophagy markers (ATG5, ATG7, Beclin-1, and LC3 B) and necroptosis markers (RIPK1, RIPK3) in NGP xenograft tumor tissues after rapamycin and MK-2206 combination treatment by Western Blot." (PMID 32116708, 2020).
tumor (continued). "In these mouse models, essential autophagy genes, such as ATG5, ATG7, ATG13 or ULK1, are deleted in genome of tumor cells that arise spontaneously in the context of a normal tumor microenvironment and functional immune system." (PMID 32308763, 2020). "Compared with normal tissues, tumor tissues showed significantly higher mRNA levels of the following key autophagy genes: ATG5, ATG7, ATG3, ATG9A, ATG9B, ATG12, AMBRA1, and NBR1." (PMID 32582551, 2020). "However, CQ represses the proliferation of ATG7-deficient cancer cells, indicating that CQ might exert its tumor inhibitory effect independent of autophagy inactivation." (PMID 31637005, 2019). "Autophagy-related gene 7 (ATG7) induces the binding of β-catenin to the promoter sequences of OCT4 to increase the expression of OCT4, which promotes self-renewal, tumor initiation, and drug resistance." (PMID 31799196, 2019). "Although oncogenic RAS-expressing atg5−/- or atg7−/- cells display reduced tumor growth, we found that CDH1 expression was largely reduced in oncogenic RAS-expressing atg7−/- or atg5−/- tumors compared to oncogenic RAS-expressing Atg7+/+ or Atg5+/+ tumors." (PMID 30782064, 2019). "We analyzed the effect of metformin in tumor initiation using the NIH/3T3 cells and the ATG7-silenced NIH/3T3 clones." (PMID 30635619, 2019). "When the Atg7 was deleted in the mice lungs bearing NSCLC, a suppression of the tumor cell proliferation was noticed." (PMID 29643976, 2018). "The mentioned miRNAs can also increase the expression of autophagy genes including ULK1, ATG7, or p62, trigger autophagy, and suppress HCC tumor growth." (PMID 29643976, 2018). "Unexpectedly, the knockdown of ATG7 dramatically inhibited UMUC3 xenograft tumor growth and reduced the tumor burden (weight) compared with the UMUC3(Nonsense) group (p < 0.01, n = 5)." (PMID 28624205, 2017). "Inhibiting autophagy using chloroquine or by downregulating ATG7 using shRNA further upregulated apoptosis, suggesting autophagy was probably was protective to PS-PDT-treated tumor cells." (PMID 28031534, 2017). "Autophagy undergoes both short- and long-term activation during cachexia; accordingly autophagy-related transcripts Bnip3, LC3b, GABARAPL1, Atg7, and CathepsinL were considerably increased in vehicle and (−)-JQ1-treated C26-tumor-bearing mice." (PMID 29167426, 2017). "For example, CD73 and CD133 have been shown to impact drug-mediated anti-tumor immune responses, and IMP3 regulates the drug resistance proteins, ABCG2 and HSF1, as well as autophagy related protein 7 (ATG7)." (PMID 26126114, 2015). "Another two autophagy markers, autophagy-related protein 7 (Atg7) and Atg6 (also known as Beclin-1), were also found to be decreased in PyVT(+/−)ADN(−/−) tumor cells." (PMID 24113220, 2013). "ATG-7, a pivotal E1-like enzyme in the autophagic cascade, is frequently overexpressed within the breast TME and plays a central role in autophagosome formation, tumor growth, invasion, and immune evasion." (PMID 41550506, 2026). "Additionally, administration of the autophagy inhibitor 3-methyladenine (3-MA) led to increased MTOR expression and downregulation of ATG5, ATG7, and BECN1, resulting in reduced tumor volume and elevated apoptosis cell death." (PMID 41502518, 2025). "In addition, other autophagy-related proteins (ATGs), including ATG7, ATG9B, and ATG16L1, also play important roles in tumor suppression." (PMID 40231206, 2025). "Similarly, treatment with the ferroptosis activator (Erastin) not only suppressed tumor volume but also decreased the expression of autophagy-related proteins (ATG5, ATG7, and BECN1), along with increased cell apoptosis." (PMID 41502518, 2025). "ATG7 protein levels also is evaluated in tumor and non-tumor tissues from PC microarray, but the difference was not significant." (PMID 38385083, 2024).
tumor (continued). "Among the fourteen ferritinophagy-related genes studied, ten exhibited significant differences between tumor and normal samples: NCOA4, FTH1, FTL, SNCA (all p < 0.0001), BECN1 (p = 0.031), ELAVL1 (p = 0.00023), TNF (p = 0.00074), ATG16L1, ATG7, and ZFP36 (all p < 0.0001)." (PMID 39593730, 2024). "The results revealed that genetic targeting or pharmacological inhibition of ATG7 had no discernible effect on either tumor growth or tumor weight in nude mice." (PMID 38627815, 2024). "The sole deletion of ATG7, without concurrent genetic alterations, induced tumor formation exclusively in the liver." (PMID 38612567, 2024). "From the results, we noticed that tumor cells highly expressed AUP1 significantly correlated with proliferation marker (MCM2, MCM6), PI3K-AKT-MTOR pathway (Akt1, TSC1, mTOR, Foxo1), and autophagy signaling (Atg3, Atg4B, Atg4D, Atg7, Atg9A, Atg16L1) in IDH wildtype tumor cells." (PMID 37029364, 2023). "A representative sample of the tumor was chosen and transferred into a new block of paraffin, the recipient block, to perform immunohistochemical analysis with the primary antibodies anti-CD44, PD-L1, and ATG7." (PMID 37173926, 2023). "FBXW7 increased BECN1, Atg7, and LC3 levels in CAL27 xenograft tumor model." (PMID 37249289, 2023). "Transplantation of FoxO1–expressing cancer cells after stable knockdown of Atg7 showed no tumor suppressive effect, demonstrating that FoxO1 exerts tumor suppressor activity by inducing autophagic cell death." (PMID 37762548, 2023). "The lack of epithelial Atg7 did not prevent tumor formation in response to 7, 12-dimethylbenz(a)anthracene (DMBA) as the initiator and 12-O tetradecanoylphorbol-13-acetate (TPA) as the promoter of tumor growth." (PMID 36429119, 2022). "For example, autophagy-related protein 7 (Atg7) and butyrate could inhibit the phosphorylation of PKM2 at tyrosine 105 and reverse the aerobic glycolysis, thereby impeding tumor cell proliferation and EMT." (PMID 35706397, 2022). "Drug-mediated anti-tumor immune responses, for instance, are influenced by CD73 and CD133, and IMP3 controls the drug resistance proteins ABCG2 and heat shock factor 1 (HSF1), as well as the autophagy-related protein 7 (ATG7)." (PMID 36358602, 2022). "In the absence of Atg7, non-tumor-bearing mice reached a similar age as animals with malignant disease." (PMID 35372352, 2022). "We conclude that tumor cell proliferation under metabolic drug treatment is not only dependent on ATG7, but also to an equal extent on BECN1, LC3, and ATG10." (PMID 35681458, 2022). "In contrast to a report on the protective effects of Atg7 deletion in UV-dependent carcinogenesis, the deletion of Atg7 did not significantly alter the rate of tumor formation in our models." (PMID 36429119, 2022). "On the other hand, in the absence of ATG7, cancer cell proliferation is inhibited, and the tumor develops into benign eosinophil tumor instead of adenoma and cancer, thereby prolonging the lifespan of mice." (PMID 35600411, 2022). "Further RT-PCR showed a substantial decrease in miR-375 expression in tumor-bearing tissues of the lncRNA TINCR overexpression group compared to the vector-control group, whereas ATG7 expression was shown to be considerably upregulated in tumor tissues that overexpressed lncRNA TINCR (vector-TINCR)." (PMID 36157234, 2022). "Regulatory T (T regs) cells exert their immune suppressive functions on other immune cells and hence maintain tolerance for tumors; upon deletion of ATG7 from T regs, the suppressor function was compromised and anti-tumor CD8 + T cells infiltrated, which resulted in the inhibition of tumor growth." (PMID 33573362, 2021).
tumor (continued). "IGF-1R knockdown via NVP-AEW541, 3-MA, and Atg7 siRNA could induce TNBC cell-protective autophagy and thereby attenuating the efficacy of IGF-1R-modulating therapeutic agents in tumor cells." (PMID 33768092, 2021). "In support of this contention, knockdown of ATG7 and VPS34, key players for autophagy activation, suppressed tumor growth induced by MAGEA6 downregulation, consistent with autophagy activity playing a key role in promoting tumor growth in response to MAGEA6 depletion in BxPC-3." (PMID 32270762, 2020). "Next, to determine if autophagy induction in tumor cells by anti–PD-1 Ab is a major contributor to the reduced efficacy of anti–PD-1 therapy, CRISPR/Cas9 gene editing was used to knock out an essential autophagy gene Atg7 in B16 cells." (PMID 32780726, 2020). "Taken together, the role of Atg7 for non-transformed as well as for tumor cells remains controversial and appears to be context and cell-type dependent." (PMID 32046105, 2020). "Comparatively, deletion of downstream autophagy genes Atg5 or Atg7 permitted development of benign tumors that failed to progress to malignant cancers." (PMID 33381037, 2020). "Then, acetylated FoxO1 binds to ATG7 in the cytosol, leading to ACD and tumor suppression activity." (PMID 32591647, 2020). "Additionally, the excised tumor masses showed that GAS8-AS1 overexpression triggered an increase in GAS8-AS1, ATG5, and ATG7 and a reduction in miR-187-3p and miR-1343-3p." (PMID 33230459, 2020). "Whole-body deletion of Atg7 in a mice model triggered a bigger regression of KRAS-driven tumors than the knockdown of cancer-specific autophagy, suggesting that basal autophagy facilitates tumor growth." (PMID 33510635, 2020). "In scope of a translational setting, it is important to determine tumor cell specificity of the observed cell death induction in the absence of Atg7." (PMID 32046105, 2020). "We found that less HMGB1 proteins were present in tumor and non-tumor tissue of the Atg7ΔHep liver, as compared with the Atg7 F/F liver." (PMID 32382012, 2020). "To unveil whether IFT88 silencing promotes tumor phenotype by activating autophagy, we used si-IFT88 and si-ATG7 to cotransfect HCC cells and then detected tumor properties." (PMID 31662980, 2019). "Our results show that the silencing of the Atg7 gene leads to an increased cell transformation of the non-tumorigenic NIH/3T3 cells induced by tumor promoters." (PMID 30635619, 2019). "In KRAS-mediated lung tumors, the depletion of Atg5 or Atg7, two mitophagic effectors involved in LC3/GABARAP lipidation, has induced a reduction in tumor burden and an increase in survival compared to the counterpart even if malignancies present a faster tumor-initiation stage." (PMID 31210843, 2019). "Consistent with the ATG7 negative regulation of HNRNPD in vitro cultured UMUC3 cells, HNRNPD protein expression was markedly increased in xenograft tumor tissues attained from nude mice injected with UMUC3(shATG7) cells, and the similar change of NCL protein expression." (PMID 31016112, 2019). "Furthermore, western blotting and RT-qPCR analysis revealed an abundance of LC3I/II, ATG7, Beclin1 and PIK3C3 in tumor samples from mice treated by juglanin." (PMID 29212196, 2017). "Furthermore, systemic genetic ablation of Atg7 in mice with established NSCLC, promoted tumor regression before damage occurred to the normal tissues." (PMID 28725634, 2017).